BTK (Bruton tyrosine kinase)
Diseases named in the same sentence as BTK in open-access papers (continued):
Sharing a sentence is not in itself a finding about the gene and the disease.
breast cancer (35 papers, 2014 to 2025). A primary or metastatic malignant neoplasm involving the breast. "Recently, an alternative isoform of BTK (BTK-C) was found to be overexpressed in breast cancer cells and was associated with cell survival." (PMID 36139701, 2022). "One study found that 30% of breast cancer tissues stain positively for BTK and that among 23 HER2-positive human breast cancer tissues 43% were positive for BTK with a statistically significant association of expression of BTK with HER2 expression." (PMID 29561760, 2018). "Similarly, numerous studies have shown that BTK inhibition causes substantial cytotoxicity to HER2+ breast cancer cells, inhibits their proliferation and clonogenicity, and diminishes their resistance to chemotherapy both in vitro and in vivo." (PMID 33937249, 2021). "LFM-A13, the first small-molecule inhibitor of Bruton’s tyrosine kinase (BTK), has demonstrated efficacy in curbing tumor growth, with additional anti-proliferative and pro-apoptotic effects observed in breast cancer models." (PMID 40672391, 2025). "Accordingly, parallel phenotypes have been documented in BTK-deficient mice, during CAR-T cell production, and in HER2-positive breast cancer stem cells, highlighting the broad role of BTK in cell fate determination." (PMID 41463321, 2025). "Collectively, the combined inhibition of FTO and BTK exhibited substantial synergistic anticancer effects in breast cancer." (PMID 41281757, 2025). "For example, BTK regulates tissue plasminogen activator-induced invasion of breast cancer cells by activating matrix metalloproteinase-9." (PMID 37638060, 2023). "In agreement with the insensitivity of HER2-negative breast cancer cells to the studied BTK inhibitors, the control cell line MCF7 also showed no decrease in colony formation after treatment with any of the compounds." (PMID 36913160, 2023). "The efficiency of ibrutinib in these cancers has already been proposed in previous publications, and we indeed found ibrutinib to be the most potent BTK inhibitor of ERBB signalling in breast cancer cell lines, once again confirming its anticancer effects." (PMID 36913160, 2023). "The anticancer effect of the BTK inhibitors ibrutinib, acalabrutinib, tirabrutinib, evobrutinib and zanubrutinib was evaluated in a panel of ten breast cancer cell lines in vitro." (PMID 36913160, 2023). "In our study, we therefore aimed to examine the potential repurposing of zanubrutinib and other selected BTK inhibitors in breast cancer cell line models." (PMID 36913160, 2023). "In conclusion, our results support the potential indication of the BTK inhibitor zanubrutinib for use in HER2-amplified breast carcinomas." (PMID 36913160, 2023). "In MDSCs, BTK is required for their development and function, and targeting of BTK with ibrutinib in mouse models of breast cancer and melanoma resulted in a reduction in MDSC frequency." (PMID 36175961, 2022). "The inhibitor of Bruton's tyrosine kinase (BTK), ibrutinib, was reported to inhibit the generation and modulate the function of MDSCs in mammary tumors and melanoma to enhance immune-based therapy." (PMID 35585567, 2022). "All these findings provide evidence that isoforms of BTK are potential targets for the treatment of epithelium-derived tumors such as breast cancer, gastric carcinoma, ovarian cancer, GBM, and prostate cancer." (PMID 34307353, 2021). "For example, related sequelae such as increased glucose uptake and protection from apoptosis result from BTK expression in breast cancer cells." (PMID 34307353, 2021). "A novel oncogenic isoform of BTK with a survival-promoting function is abundantly expressed in breast cancer, ovarian cancer, prostate cancer, and colorectal cancer." (PMID 33937249, 2021). "In their breast cancer model, a similar effect was found despite BTK negativity and low PD-L1 expression." (PMID 32532074, 2020).
breast cancer (continued). "We also explored the level of BTK expression in breast cancer samples obtained from patients and the effects of LFM-A13 alone and in combination with Epo on cell cycle progression." (PMID 32912025, 2020). "Our present study is based on DC-mediated anticancer therapy using the potent ITK/BTK inhibitor ibrutinib in a murine model of breast cancer." (PMID 32025027, 2020). "BTK-C, an isoform of BTK, was expressed in 30% of breast cancer tissue, with an even higher percentage (43%) in HER2+ tumors." (PMID 32532074, 2020). "LFM-A13 is first inhibitor of Bruton’s tyrosine kinase (BTK) which decreases tumour progression in the MMTV/Neu transgenic mouse model of HER2 positive breast cancer as effectively as paclitaxel and gemcitabine." (PMID 32912025, 2020). "To understand the molecular mechanisms of the antiproliferative effect of the simultaneous use of Epo + LFM-A13, we assessed BTK expression in breast cancer cells." (PMID 32912025, 2020). "The administration of Epo + LFM-A13 resulted in a decrease of BTK expression in both breast cancer lines." (PMID 32912025, 2020). "Ibrutinib has been reported to play a valuable role in inhibiting activity of BTK‐C, a novel isoform of BTK that protects breast cancer cells from apoptosis." (PMID 31408580, 2019). "Inhibition of BTK in pre-clinical models of pancreatic cancer, breast cancer and BTK-negative colon cancer have shown only marginal improvement of survival as monotherapy, but when combined with chemo- or immunotherapy, survival was greatly enhanced." (PMID 29455639, 2018). "A novel isoform of BTK (BTK-C) has also been described as expressed in several human breast cancer cell lines and tumor tissues at relatively low levels, yet still providing an important function in protecting breast cancer cells from apoptosis." (PMID 29561760, 2018). "In line with this, we investigated whether FTO and BTK influence OS in breast cancer patients through c-Myc and E2F1." (PMID 41281757, 2025). "BTK’s gene expression is in the 46th percentile compared to all cell lines and the 48th percentile in breast cancer cell lines, while its copy number is in the 93rd percentile compared to all cell lines and the 81st percentile in breast cancer cell lines." (PMID 38371918, 2024). "BTK regulates breast cancer metastasis by activating PLC γ2/PKC signaling." (PMID 36986499, 2023). "However, in TPA-induced breast cancer cells BTK is also involved in the PLCγ-dependent NF-κB activation, leading to the upregulation of metalloproteinase-9, crucially involved in cancer cell invasion." (PMID 36612306, 2023). "Subsequent studies found that BTK was detected in various cancers, including colon cancer and breast cancer, suggesting that BTK protein may play a role in the development of other cancers." (PMID 37638060, 2023). "BTK inhibition is crucial to inhibit breast cancer metastasis." (PMID 36986499, 2023). "BTK inhibition prevents lapatinib-resistant breast cancer clones from arising." (PMID 34307353, 2021). "However, it has been reported that an isoform of BTK (BTK-C) is expressed in breast cancer cells and enhances cancer cell proliferation." (PMID 34077419, 2021). "In addition, current studies have shown that BTK inhibitors can be used to treat solid tumours, such as colon cancer, breast cancer and gastric carcinoma, by promoting tumour cell apoptosis." (PMID 34457331, 2021). "This might explain its greater impact on HER2+ cells and provide a strong rationale for its clinical use, especially since a correlation between the expression of HER2 and BTK was found in human breast cancer tissue." (PMID 32532074, 2020). "Together, our findings indicate that ibrutinib and other BTK inhibitors could be novel drugs for the treatment of breast cancer." (PMID 32025027, 2020). "Fifty-five cases of primary breast cancer out of 90 (61.11%) were positive for BTK." (PMID 32912025, 2020). "BTK has been classified as a gene whose expression protects breast cancer cells from apoptosis." (PMID 32912025, 2020).
breast cancer (continued). "BTK and Src, which are involved in the apoptosis pathway that is induced by anticancer drugs, may also influence the malignancy of breast cancer." (PMID 32110969, 2020). "Thus, the presence of BTK in breast cancer cells may contribute to the effect of BTK inhibitors in HER2-positive cells." (PMID 36913160, 2023). "However, BTK inhibitors have been extended to treat some of the solid tumors, such as non-small cell lung cancer, breast cancer, and pancreatic cancer, suggesting that BTK may affect other immune cells in various TMEs." (PMID 34805160, 2021). "Recently, it was reported that BTK inhibitors exerted potential beneficial effects against numerous types of solid tumour, including glioblastoma multiforme and breast cancer; however, whether BTK is crucial for the progression of bladder cancer remains unclear." (PMID 33918597, 2021). "The differences in BTK expression observed between a primary cancer and related metastases in the same patient or in different patients bearing breast cancer may indicate the presence of a tumour heterogeneity, which can strongly influence the choice of the more appropriate clinical management." (PMID 32912025, 2020). "This is consistent with other research that found that BTK is expressed in MDSC, and ibrutinib leads to a considerable decrease in MDSC in mouse models of breast cancer and melanoma." (PMID 36903645, 2023). "Indeed, ibrutinib treatment significantly decreases metastatic dissemination of tail vein-injected breast cancer cells to the bone; however, it is not known whether decreased osteotropism caused by BTK inhibition is a cancer cell autonomous effect." (PMID 34307353, 2021). "In our study, the presence of BTK in both MCF-7 and MDA-MB-231 cell lines as well as in primary and metastatic breast cancer tissues has been confirmed." (PMID 32912025, 2020). "In our study for the first time, we evaluated the effect of simultaneous use of Epo and Bruton’s tyrosine kinase (BTK) inhibitor LFM-A13 on the viability and tumour development of breast cancer cells." (PMID 32912025, 2020). "Separately, ibrutinib, as well as other BTK inhibitors spebrutinib and CGI- 1746, were shown to reduce breast cancer cell survival and prevent drug resistant clones from arising." (PMID 29561760, 2018). "In sum, FTO and BTK are important regulators of c-Myc and E2F1 accumulation in breast cancer, and their induction of low expression levels is a major factor in improving the survival outcomes of breast cancer patients." (PMID 41281757, 2025). "Collectively, these findings highlight dual inhibition of FTO and BTK as a promising therapeutic strategy for maintaining low c-Myc and E2F1 expression levels, thereby improving survival outcomes and guiding future clinical management of breast cancer." (PMID 41281757, 2025). "The molecular weight of BTK-C is 79.9 kDa, and its expression is detectable using a commercial antibody against BTK-A; however, in our study, we were not able to detect the expression of BTK in any of the tested breast cancer cell lines." (PMID 36913160, 2023). "Hence, BTK inhibition shall inhibit the expression of MMP-9 initiated by TPA, thereby suppressing breast cancer metastasis." (PMID 36986499, 2023). "Indeed, our studies show that several BTK inhibitors, including ibrutinib, AVL-292 (spebrutinib) and acalabrutinib, effectively inhibit breast cancer and prostate cancer cell growth." (PMID 34307353, 2021). "The explanation of the susceptibility of these two cell lines to the tested compounds may be indirectly related to the BTK protein, which is involved in the development of CML and breast cancer." (PMID 32110969, 2020). "Apart from BTK inhibition, ibrutinib also blocks the activation of EGFR, human epidermal growth factor receptor 2 (HER2), Erb-B2 receptor tyrosine kinase 3 (ErbB3), and Erb-B2 receptor tyrosine kinase 4 (ErbB4), which results in increased apoptosis of breast cancer cells." (PMID 36903645, 2023).
myeloma (35 papers, 2013 to 2024). "BTK knockdown myeloma cells had altered the expression of genes associated with adhesion and proliferation and increased mammalian target of rapamycin signaling." (PMID 25083818, 2014). "Not only do these mutations help distinguish between WM and other similar hematologic malignancies like myeloma, but they are also predictive with regards to response rates to ibrutinib and other Bruton’s tyrosine kinase (BTK) inhibitors in WM." (PMID 39417016, 2024). "BTK is highly expressed in malignant cells and certain cell lines of many patients with multiple myeloma (MM)." (PMID 37638060, 2023). "The BTK inhibitor ibrutinib is now in use in combination with other anti-myeloma agents in relapse and refractory clinical trial settings." (PMID 35328533, 2022). "Yet, despite the presence of these compensatory pathways, complete silencing of BTK expression is cytotoxic to MM1R cells, emphasizing BTK’s involvement in myeloma cell survival." (PMID 33807411, 2021). "Enforced expression of BTK in this cancer enhances the features of cancer stemness and its resistance to conservative myeloma chemotherapy." (PMID 34577576, 2021). "Bruton’s tyrosine kinase (BTK) is a regulator of myeloma stemness and senescence and is related to MM progression and drug resistance." (PMID 33918655, 2021). "The overexpression of BTK in myeloma cells can increase their clonogenic ability and drug resistance, while inducible knockout of BTK abolished them." (PMID 34298738, 2021). "In mice, LFM-A13 has had similar effects on myeloma cell growth, homing to bones and resorption, and the same is true of other BTK inhibitors such as ibrutinib." (PMID 34071917, 2021). "In multiple myeloma, an elevated expression of BTK leads to Akt/Wnt/BTK-dependent upregulation of key stemness genes (OCT4, SOX2, NANOG, and MYC) and enhanced self-renewal." (PMID 34577576, 2021). "The BTK pathway has been shown to provide survival for malignant clone and multiple myeloma stem cells (MMSCs)." (PMID 34071917, 2021). "Studies in which BTK was blocked using Ibrutinib in myeloma cells showed inhibition of tumor survival and proliferation through the NFκB, STAT3, ERK1/2 and AKT signaling pathways." (PMID 34071917, 2021). "In particular, the AKT/Wnt/β catenin pathway dependent upregulation of key stemness genes NANOG, OCT4, SOX2 and MYC have been observed in myeloma cells overexpressing BTK." (PMID 34071917, 2021). "In multiple myeloma (MM), a malignancy of plasma cells in the bone marrow, BTK was shown to be overexpressed, whereby BTK activated AKT signaling, leading to down-regulation of P27 expression and upregulation of key stemness genes." (PMID 29455639, 2018). "Our previous study also revealed that BTK inhibitor CGI-1746 inhibits both clonogenic myeloma stem-like cells and bulk MM cells from primary patient samples and cell lines." (PMID 28915637, 2017). "We previously explored the role of BTK in maintaining multiple myeloma stem cells (MMSCs) self-renewal and drug-resistance." (PMID 28915637, 2017). "A very similar fraction of BTK high-expressing myeloma and BTK–dependent reduction in survival was also observed in the Total Therapy 3 (TT3) cohort." (PMID 28915637, 2017). "The results presented in this figure provided the preliminary evidence for a role of BTK suppressing myeloma cell senescence." (PMID 28915637, 2017). "We tested BTK expression in normal bone marrow samples (NP) and myeloma samples using immunohistochemistry (IHC) staining." (PMID 28915637, 2017). "In myeloma, up-regulation of BTK leads to increased bone resorption and homing of MM cell to the BM." (PMID 26415231, 2015). "Our most recent, unpublished work indicates that up-regulation of BTK in myeloma cells leads to phosphorylation and activation of STAT3, a crucial regulator of NANOG." (PMID 26415231, 2015). "Additional regulators of NANOG in myeloma are Hh and Wnt, two “stemness” pathways that are governed, at least in part, by BTK." (PMID 26415231, 2015).
myeloma (continued). "BTK knockdown had reduced adhesion to stroma and migration of myeloma cells toward stromal cell-derived factor-1." (PMID 25083818, 2014). "In severe combined immunodeficient-rab mice with contralaterally implanted pieces of bones, BTK knockdown in myeloma cells promoted their proliferation and growth in the primary bone but suppressed metastasis to the contralateral bone." (PMID 25083818, 2014). "Our findings highlight intratumoral heterogeneity of myeloma cells in the bone marrow microenvironment and suggest that BTK is involved in determining proliferative, quiescent or metastatic phenotypes of myeloma cells." (PMID 25083818, 2014). "The interesting role of BTK activity in myeloma cell clonogenicity and metastasis and in osteoclast-mediated bone resorption may have therapeutic potential in MBD." (PMID 35328533, 2022). "In an in vitro study, BTK inhibition reduced the migration of myeloma cells toward SDF-1." (PMID 35328533, 2022). "Additionally, the effect that BTK inhibition has on myeloma cell homing and adhesion to the bone marrow can inhibit important functions in MM survival, reducing cytokine secretion and sensitizing drug resistant cells to chemotherapy." (PMID 34071917, 2021). "Thus, we found that BTK levels in putative MMSCs are significantly higher than in bulk myeloma cells." (PMID 26415231, 2015). "Although many details have yet to be filled in, it is possible that NANOG-dependent myeloma stemness may be therapeutically targeted using small-molecule BTK inhibitors, such as ibrutinib." (PMID 26415231, 2015). "al. demonstrated that silencing BTK in myeloma cells increased the growth of individual tumor nodules, yet decreased the tumor's metastatic potential suggesting that inhibition of MMSCs with the self-renewing but relatively quiescent capacity are critical for myeloma dissemination." (PMID 26415231, 2015). "The available data support the contention that BTK is a promising therapeutic target in myeloma." (PMID 26415231, 2015). "Based on our data, overexpression of BTK leads to increased levels of NANOG in myeloma cells." (PMID 26415231, 2015). "The compound down-regulates BTK signaling in myeloma cells evident by reduced in vivo homing of myeloma cells to bone, prevention of myeloma-induced bone resorption, and moderate suppression of myeloma growth in primary myeloma-bearing SCID-rab mice." (PMID 23958373, 2013). "Additionally, the overall homing of myeloma cells has been shown to be dependent on BTK." (PMID 34071917, 2021). "Using the small-molecule inhibitor of BTK, LFM-A13, in a SCID-rab model with primary myeloma cells injected into rabbit bones, Bam and co-workers reported a suppressed osteoclast activity, less osteolytic resorption, and a moderate decrease in myeloma growth." (PMID 33917250, 2021). "The aim of the current study was to compare ibrutinib in combination with BTZ to combinations of ibrutinib with either CFZ or LU-102 with respect to the resulting effects on BTK signaling and cytotoxicity in MM cells, including BTZ-resistant myeloma." (PMID 26099967, 2015). "Similarly, by virtue of activating AKT, BTK may unleash a plethora of changes in myeloma cells, including increased survival via regulation of BCL-2 family proteins, elevated drug efflux activity via induction of ABCB1 and rearrangement of the cytoskeleton via inhibition of GSK." (PMID 26415231, 2015). "The aim of the study was to understand the role of BTK in myeloma cell growth and metastasis using the stably BTK knockdown luciferase-expressing INA6 myeloma line." (PMID 25083818, 2014). "In 176 paired clinical samples, BTK and CXCR4 expression was lower in myeloma cells purified from a focal lesion than from a random site." (PMID 25083818, 2014). "Other novel agents have also emerged for the treatment of multiple myeloma including HSP90 inhibitors, Bruton’s tyrosine kinase (BTK) inhibitors, and novel immunomodulating agents." (PMID 24314019, 2013).